SHISAL1 (shisa like 1)
Synonyms: KIAA1644
Tractability: Antibody: UniProt predicts a signal peptide or a membrane-spanning region.
Gene: Protein-coding gene on chromosome 22 (44,243,665 to 44,312,951, reverse strand). Ensembl gene ENSG00000138944.
Subcellular location: Membrane
Subcellular location (Human Protein Atlas): Cytosol; Vesicles
Gene Ontology:
Molecular function: protein binding
Cellular component: membrane
Genetic constraint (gnomAD): Loss-of-function variants: 9 observed, 22.95 expected, observed/expected ratio (o/e) 0.39, 90% interval 0.23 to 0.68. The upper end of that interval is the gene's LOEUF score, 0.68, which puts it in group 2 of 6, group 1 being the genes least tolerant of losing a copy. Missense variants: 246 observed, 284.08 expected, observed/expected ratio (o/e) 0.87, 90% interval 0.78 to 0.96. Synonymous variants: 119 observed, 121.44 expected, observed/expected ratio (o/e) 0.98, 90% interval 0.84 to 1.14.
Homologues: Orthologues: macaque SHISAL1 (100% identical), chimpanzee SHISAL1 (99% identical), pig SHISAL1 (94% identical), dog SHISAL1 (94% identical), mouse Shisal1 (93% identical), guinea pig SHISAL1 (88% identical), tropical clawed frog shisal1 (63% identical), zebrafish shisal1a (62% identical), zebrafish shisal1b (57% identical). Paralogues in human: SHISA4 (20% identical), SHISA2 (19% identical), SHISA3 (19% identical), SHISAL2A (16% identical), SHISAL2B (14% identical).
Diseases named in the same sentence as SHISAL1 in open-access papers:
SHISAL1 is named in the same sentence as 4 diseases in open-access papers, as found by Europe PMC text mining. Sharing a sentence is not in itself a finding about the gene and the disease.
SHISAL1 shares sentences with these, for which no sentence is quoted: tumor (2 papers); breast tumors (1); cancer (1); endometrial cancer (1).